MTMR9LP (myotubularin related protein 9 like, pseudogene)
Synonyms: formerly MTMR9L
Gene: Transcribed unprocessed pseudogene on chromosome 1 (32,231,847 to 32,241,592, reverse strand). Ensembl gene ENSG00000220785.
Diseases named in the same sentence as MTMR9LP in open-access papers:
MTMR9LP is named in the same sentence as 1 disease in open-access papers, as found by Europe PMC text mining. Sharing a sentence is not in itself a finding about the gene and the disease. The quoted sentences say what the papers report.
Cryptococcal meningitis (1 paper, 2019). Meningeal inflammation produced by cryptococcus neoformans, an encapsulated yeast that tends to infect individuals with acquired immunodeficiency syndrome and other immunocompromised states. "The expression of the lncRNAs, ECRP, LINC00968, DPY19L1p1, DEFA8P, and DEFT1P2 was higher but the expression of the lncRNAs DDX11L10 and MTMR9LP was lower in cryptococcal meningitis patients than in healthy controls, which was consistent with the chip analysis results." (PMID 30767376, 2019).